STAT1 (signal transducer and activator of transcription 1)
Diseases named in the same sentence as STAT1 in open-access papers (continued):
Sharing a sentence is not in itself a finding about the gene and the disease.
tumor (continued). "Our above observations indicate that survivin expression in the tumor-specific CTLs is not only differentially induced by tumor cells and CD3 mAb stimulation but also correlated with STAT1 activation, suggesting that survivin might also be a target gene of the IFN-γ signaling pathway." (PMID 21124930, 2010). "Nevertheless, two key enzymes responsible for the maintenance of tumour glycolysis in aerobic conditions - lactate dehydrogenase A (LDHA) and pyruvate kinase type M2 (PKM2) - were among those identified in our analysis as up-regulated by STAT1 at both the gene and protein level." (PMID 19891767, 2009). "In addition, IR drastically suppressed the GG pathway in STAT1 KD tumours without significant change in STAT1 WT tumours." (PMID 19891767, 2009). "To study mechanisms providing tumour resistance to endogenous IFNγ, we analysed primary TGCT and two human TGCT cell lines (NTERA and NCCIT) for the expression of IFNγ receptor and for the level of phosphorylation of the signal transducer and activator of transcription (STAT)-1." (PMID 12942126, 2003). "However, STAT1 might not be a targetable factor, since it can act as either an oncoprotein or tumor suppressor in some malignant cells, depending on genetic background." (PMID 38351096, 2024). "In addition, a recent study highlighted that increased STAT1 expression in tumor cells was strongly indicative of an immunogenic microenvironment, characterized by significantly high expression levels of MHC class I and PD-L1, both on tumor and non-tumor cells." (PMID 36982677, 2023). "Therefore, inhibition of STAT1/HMGB1 may enhance cisplatin chemotherapy in tumors and protect kidneys from chronic nephrotoxicity, an intriguing possibility that requires further tests in tumor-bearing animal models." (PMID 37284446, 2023). "Similarly, STAT1 activation may induce antiproliferative and proapoptotic responses and enhance antitumor immunity during carcinogenesis, while STAT3 activation enhances tumor cell survival/proliferation, motility, and immune tolerance." (PMID 36059536, 2022). "However, when compared to normal tissue, STAT1 has no significant elevation in PCa tumour." (PMID 35908276, 2022). "Our previous studies have demonstrated that a lack of STAT1 renders mice highly susceptible to CAC, which correlates with rapid and extensive intestinal damage, increased cell proliferation in the early stages of injury-induced tumor formation, and reduced apoptosis in advanced tumors." (PMID 34299314, 2021). "Thus, inhibiting STAT3 to block tumor growth without affecting STAT1 is a challenging task." (PMID 33805945, 2021). "However, the tumor cell-intrinsic role of Stat1 in CRC is not well defined." (PMID 32444775, 2020). "Interestingly, we could neither identify a significant correlation between tumor cell‐intrinsic nuclear STAT1 expression and vein invasion nor lymph node metastasis in both sexes." (PMID 29419930, 2018). "However, therapeutic intervention could not reverse the tumor cell-induced STAT1 suppression (0.62±0.13) and STAT3 activation (2.65±1.07) in the lung tissues." (PMID 21931823, 2011). "We observed that tumour cells activate the STAT3 and STAT1 signalling pathways, but not the PI3K–AKT or MAPK pathways, after the IL‐11 challenge." (PMID 40673604, 2025). "We observed in both patients that IDO1 positive tumor cells displayed a higher percentage of GLI and STAT1/IRF1 double positive cells than IDO1 negative tumor cells." (PMID 39962447, 2025). "There was little or no STAT1 expression even after IFN treatment in some tumor cells and tumor-derived cell lines, and STAT1-depleted cells resisted apoptosis in response to TNF or IFN-gamma." (PMID 40241721, 2025). "Depletion of Ptdss1 in tumor cells increased expression of interferon-γ (IFN-γ)–regulated genes, including B2m, Cxcl9, Cxcl10, and Stat1, even in the absence of IFN-γ stimulation in vitro." (PMID 40929270, 2025).
tumor (continued). "Despite these data were not related to an increased IFNG mRNA expression in tumor tissues, an activation of the canonical IFN-γ signaling pathway was demonstrated with an increased Stat1 phosphorylation and ISG15 expression." (PMID 40393975, 2025). "When tumor infiltrating lymphocytes (TIL) were added to parental MOC1 cells, a proportion of the tumor cells were killed by 72 h; in contrast, STAT1-/- cells were not killed when TIL were added." (PMID 38231444, 2024). "Inhibited the anti-tumor effect of IFN-γ and up-regulate the expression of negative feedback regulator PIAS1 by activating the JAK/STAT1 pathway." (PMID 39906741, 2024). "Once again, this underscores how deletion of STAT1 in mice allows them to stay responsive to CRT/E7 vaccination, although it does not facilitate full tumor growth protection like that in vaccinated control mice." (PMID 38675812, 2024). "We actually noted that the electrical impedance increased in STAT1-/- cells after TIL were added, likely as a result of T cells floating to the bottom of the well without killing any tumor cells." (PMID 38231444, 2024). "Based on the Spearman correlation analysis in GEPIA, we identified a significant correlation between STAT1 and LDHA/LDHB/FGF1/FGF2 in tumor tissues but not in normal tissues." (PMID 38764020, 2024). "STAT1 or STAT3 knockdown by siRNA reduces cytokine-induced expression, but not constitutive PD-L1 expression in human monocytes and tumor cells." (PMID 38022653, 2023). "Tumor development in four mouse models lacking IFN-γ and/or STAT1 function was threefold higher than that in syngeneic wild-type mice, indicating that IFN-γ and lymphocytes mediate the tumor suppressor pathway in immune surveillance." (PMID 36900322, 2023). "Referring to the TCGA HNSC tumor dataset, we found a positive correlation between IFN-γ-related genes (IFN-γ, CD8A, and STAT1) and PD-L1 (CD274), but not between EGF-related genes (EGFR, AKT1, and MAP2K7), which seems to support the results of this study." (PMID 35456895, 2022). "The definitions of positivity of STAT1, PD-L1, CD4, and CD8 were defined as positive expression on ≧ 1% of tumor cells or non-tumor cells, respectively." (PMID 34758826, 2021). "Through IFN-γ/STAT1 pathway activation, IFN-γ inhibits tumor cell proliferation and establishes tumor dormancy without destroying malignant cells." (PMID 34867958, 2021). "For evaluation of STAT1 expression, we did not define a cut-off for a “STAT1-positive” and a “STAT1-negative” group but used the TPS (percentage of positive tumor cells of all tumor cells), taking cytoplasmatic staining into account." (PMID 34572789, 2021). "Lack of signal transducer and activator of transcription 1 (STAT1), JAK1, or IFNGR1 in BRAFV600E/PTEN-/- mice increased tumor growth and decreased survival after anti-PD-1 treatment." (PMID 34827646, 2021). "Our analyses showed that both tumor and nontumor cells expressed IFN signaling genes such as STAT1, STAT2, ISG15, OAS1, and MX1 in all three datasets." (PMID 34771447, 2021). "In addition, STAT1 may exert negative impact on tumor immune surveillance." (PMID 32275681, 2020). "For example, STAT1 induced expression of PD-L1 upon IFN-γ stimulation in non-transformed and tumor cells, which inhibited T cell and NK cell functions." (PMID 32275681, 2020). "Surprisingly, we found that p-STAT1 is completely absent in our HCC tumor tissues and HCC cell lines, indicating that u-STAT1 is the dominant form located in both nuclear and cytoplasm." (PMID 30456450, 2019). "Studies in patients have suggested a negative correlation between STAT1 and CRC tumorigenesis and tumour cell proliferation, and STAT1 has been proposed as a biomarker for good prognosis in CRC." (PMID 30538296, 2019).
tumor (continued). "siRNA knockdown of STAT1 but not STAT3 reduced IFN-g- and IL-27-induced PD-L1 protein expression on tumor cells." (PMID 31730010, 2019). "The mRNA levels of TGM2, USP18, DDX58, PARP9, STAT1 and STAT2 were not significantly different between ER--tumor tissues and their corresponding tumor-adjacent tissues." (PMID 29416786, 2018). "The protein levels of STAT1 and IRF1 were significantly correlated in the normal but not in the tumor tissues." (PMID 30305853, 2018). "For example, although IL-27 can simultaneously activate STAT1 and STAT3, the activation of STAT1 rather than that of STAT3 mediates the tumor suppressor role of IL-27." (PMID 28626343, 2017). "Taken together, these data showed that STAT1 reduced SLUG expression and mediated the OSM-dependent suppression of cell motility in vitro and tumor metastasis in vivo, while STAT3 did not interfere with this effect even though it was phosphorylated." (PMID 27486982, 2016). "In this study, a triad of type I IFN-signaling pathway genes, STAT1, ISG15, and IFIT1, formed a pan-tumor-type negative prognostic factor, and a broader seven-gene cluster established negative prognostic criteria for treatment-resistant breast cancer." (PMID 28548066, 2014). "Thus, NOS1 inhibition of IFNs signaling activation in tumor cells primarily occurs during the initial phase of cellular response to PRR signaling, rather than through disruption of components in the JAK/STAT1 pathway." (PMID 41535256, 2026). "Given the enhanced activation pattern of STAT1-∆N with respect to tyrosine phosphorylation, we subsequently investigated the mRNA expression of STAT-mediated target genes in tumor cells isolated from transgenic mice compared to cultured non-transformed cells from WT animals." (PMID 40287766, 2025). "Nevertheless, while the vaccinated STAT1−/− mice did not resist tumor growth entirely, the host immune system in STAT1−/− mice remains responsive to CRT/E7 vaccination by significantly slowing down tumor progression." (PMID 38675812, 2024). "Moreover, IL-17 can inhibit the anti-tumor effects of IFN-γ and up-regulate the expression of the negative feedback regulator PIAS1 by activating the JAK/STAT1 pathway, thereby accelerating HCC development." (PMID 39906741, 2024). "In this context, it would be interesting to explore whether butyrate can also be involved in the absence of STAT1 activation partially helping to inhibit PD-L1 expression in CRC, thereby enhancing the cytotoxicity of T-cells to tumor cells." (PMID 37931529, 2023). "Indeed, in T cell-specific PTPN2-deficient mice, Compound 182 had no significant additional effect on STAT-1 signaling and TILs and only moderately enhanced T cell cytotoxicity and the repression of AT3-OVA tumor growth." (PMID 37500611, 2023). "One issue is that the role of STAT1 in OSCC may not actually correlate with expression levels within the tumor itself, but rather with the immune cells constituting the inflammatory tumor milieu." (PMID 35844493, 2022). "Consequently, JAK–STAT activation, in a JAK1/JAK2- and STAT1/STAT3-dependent manner, is required for the transition to a stem-like, multilineage and EMT state but not for the tumor cells that have completely redifferentiated to an NE-like lineage." (PMID 36065066, 2022). "Interestingly, more recently, concomitant absence of STAT1 and STAT3 was reported in CRC tumor tissue, which was found to be significantly correlated with shorter overall survival of CRC patients." (PMID 33846436, 2021). "However, in contrast to human studies, STAT1, but not STAT3 or STAT6, was responsible for immunosuppressive activity of TAMs derived from colon CT-26 tumor-bearing BALB/c mice." (PMID 32486098, 2020). "Thus, we wonder why cells choose to response to the suppressive effect of STAT1 rather than the activation effect of STAT3 in terms of SLUG expression, cell motility, and tumor metastasis, while OSM activates both." (PMID 27486982, 2016).
tumor (continued). "Since QPCR analysis showed more than 3-fold induction of AP2 expression by TGFβ within responsive low grade tumor cells, whereas only marginal to no change was detected in STAT3, and STAT1 transcript levels (data not shown), thus further analysis of AP2 binding was prioritized." (PMID 23840623, 2013). "In the subcutaneous tumor model, downstream signaling molecules were downregulated in the TINCR knockdown group relative to the control group, and there were no significant changes in STAT1 and p-STAT1, and the protein levels of PD-L1 and USP20 were also downregulated." (PMID 36725842, 2023). "Indeed, the combination of HDAC3 inhibitor RGFP966 with a DNA demethylation reagent, 5-aza-2-deoxycytidine, synergistically enhanced the expression of several tumor suppressors such as p16, PTEN, STAT1, CD40, and large non-coding RNA MEG3, accompanied by growth suppression." (PMID 35646715, 2022). "Cells without STAT1 gene cannot be induced to produce SOCS1 due to IFNγ signalling pathway obstruction, which may induce malignant cell proliferation, thus SOCS1 is also regarded as a tumor inhibitor." (PMID 36185620, 2022). "Interestingly, in our orthotopic HNSCC model, we found that TRIM24 expression is high in HNSCC cells but not in tumour-infiltrating T lymphocytes, suggesting the potential of targeting TRIM24 to modulate STAT1 signalling specifically in HNSCC cells but not T cells." (PMID 35595823, 2022). "The positive STAT1 expression in mCRC cells was strongly indicative of a highly immunogenic microenvironment, with significantly higher expression levels of MHC class I and PD-L1, in both tumor and nontumor parts, compared with cells with negative STAT1 expression." (PMID 34758826, 2021). "The previously identified TFs—STAT1, STAT3, KDM1A, PML RELA, and TBL1XR1—did not exhibit a deviating correlation between the early and late tumor stages, indicating that their correlation remains constant throughout the different stages of the tumor compared to non-tumor tissues." (PMID 33384992, 2020). "IFN-γ strongly increased PD-L1 and β2-microglobulin expression on RT2-cancer cells but not on RT2.Stat1−/−-cancer cells; β2-microglobulin+ cells were found in sections of RT2.Stat1−/−-cancers, showing that IFN-γ-responsive host immune cells infiltrated the tumour microenvironment during ICB." (PMID 32165639, 2020). "In the present study, the absence of STAT1 significantly increased the production of Th17 cytokines (IL-17A, IL-17F, and IL-22) but not of TNF-α and IFN-γ, indicating that a lack of STAT1 signaling induces a significant change in the microenvironment that supports inflammation and tumor formation." (PMID 30235866, 2018). "However, the therapeutic application of the complex did not suppress metastasis because the complex could not reverse tumor cell-induced STAT3 activation and neither activate IFNγ/STAT1 signaling and autophagy." (PMID 21931823, 2011). "However, studies on tumor immunity have also found that the knockout of STAT1 and STAT3 does not affect the constitutive expression of PD-L1, indicating a variety of cytokines may induce the expression of PD-L1 on tumor and/or immune cells through different signaling mechanisms." (PMID 38715061, 2024). "Dependent on the patient-specific background, differences in STAT1 and STAT3 levels, their specific activation mechanism as well as the extent of their phosphorylation may be decisive for generating either a tumour-promoting or a tumour-suppressive effect (or none of the two)." (PMID 25880691, 2015).
infection (814 papers, 2005 to 2026). The state of being infected such as from the introduction of a foreign agent such as serum, vaccine, antigenic substance or organism. "These infections are typically self-resolving but can persist in the absence of the adaptive immune system and are lethal in interferon-deficient settings, such as STAT1−/− mice." (PMID 40464581, 2025). "Following infection, incremental weight loss and additional clinical signs listed previously were recorded in Ifnar1-/- and Stat1-/- mice." (PMID 40694555, 2025). "While we demonstrated that the luminescence output from MNoVCW3-HiBiT can be used to probe replication kinetics after infection of STAT1 deficient mice, we were unable to assess in vivo bioluminescent imaging given the lack of a LgBiT expressing mouse line." (PMID 40402985, 2025). "On the other hand, infection (the SFV group) significantly upregulated M1-linked TFs Stat1, Irf9 and Klf6 expression, as well as M2-linked Stat3 expression." (PMID 40547518, 2025). "STAT1 phosphorylation was unchanged in CIC-deficient versus control cells during infection, indicating that the elevated ROS in the absence of CIC is unlikely to be driven by the IFN-STAT1 pathway." (PMID 41198672, 2025). "There is however a significant limitation in this mouse model, as STAT1-/- leave mice highly susceptible to infection due to a severe compromise of immune homeostasis, limiting our ability to assess TI-mediated protection upon S.Tm challenge." (PMID 39819562, 2025). "STAT1 plays an important role in type I and II interferon signaling, with knockout mice susceptible to infection." (PMID 39901164, 2025). "For example, MNoVCW3 causes an acute infection that spreads to extraintestinal tissues and is lethal in STAT1 deficient animals." (PMID 40402985, 2025). "The selective gene deletion of STAT1 in mice or the presence of loss-of-function mutations of STAT1 in humans both cause rapid death from severe infections." (PMID 40920886, 2025). "It is also reported that mutations within STAT1 which is an essential downstream factor in IFNα/β and IFNγ signaling pathways leads to lethal outcomes from infection with HSV-1, HCMV, and Epstein-Barr virus." (PMID 39352890, 2024). "Our data indicate that STAT1 was a major transcription factor associated with the DEGs in response to H37Rv-INH-R infection." (PMID 39597535, 2024). "The STAT1 mutation greatly impairs the type I and II interferon responses in these mice making them hypersensitive to infection." (PMID 38932403, 2024). "This demonstrates that Orf6 loss enhances IRF3 and STAT1 activation despite similar levels of infection in the first 24 h.p.i., confirming the important role of Orf6 in innate immune suppression and in distinguishing BA.5 from earlier Omicron subvariants." (PMID 38228858, 2024). "The effect of B cell-intrinsic STAT1 deficiency on acute MHV68 replication was first measured at 5 days post-infection, at the peak of MHV68 replication." (PMID 39440973, 2024). "Depletion of TBK1 caused a loss of pSTAT1 in the WT infection and, therefore, the late phase activation of STAT1 is dependent on TBK1 signaling in infection." (PMID 37289831, 2023). "The essential role of STAT1 in the IFNγ pathway has been demonstrated by the enhanced susceptibility of STAT1−/− mice to infection with mouse cytomegalovirus, Lassa virus and Listeria monocytogenes." (PMID 36748729, 2023). "Humans with gain-of-function (GOF) mutations in STAT1 (Signal Transducer and Activator of Transcription 1), a potent immune regulator, experience frequent infections." (PMID 37275873, 2023). "Mice deficient for Stat1 or otherwise rendered unresponsive to IFNs succumb within a few days to infection with only a few hundred plaque forming units (PFU) of MCMV17,18." (PMID 37248241, 2023). "Mechanistically, Stat1-deficiency promotes lytic infection but abolishes latent persistence of murine cytomegalovirus in PDGFRα-positive fibroblastic cells in vivo." (PMID 37248241, 2023).